INS (insulin)
Diseases named in the same sentence as INS in open-access papers (continued):
Sharing a sentence is not in itself a finding about the gene and the disease.
type 2 diabetes (continued). "A small molecular compound, which is a structural analogue of other molecules with antipyretic and analgesic effects, induces ATF6α nuclear translocation without the activation of CHOP and restores insulin sensitivity in type 2 diabetes." (PMID 29921793, 2018). "Insulin needs do not reach a steady state in patients with either type 1 or type 2 diabetes, as shown in the index cases in this review." (PMID 29682315, 2018). "The study consists of 58 patients with type 2 diabetes, with fasting blood sugar of 110–220 mg/dl, with same oral hypoglycemic drugs, but no insulin treatment." (PMID 29507651, 2018). "One treatment approach is the use of agents based on physiological incretins, as patients with type 2 diabetes show a relative lack of insulin." (PMID 29360748, 2018). "We will briefly consider the action of metformin and then review the major clinical trials of metformin use in pregnancy including its use in obese non-diabetic women and as an addition to insulin in type 2 diabetes." (PMID 29973490, 2018). "Few reports have suggested the lack of response to intranasal administration of INS in obese subjects and type 2 diabetes." (PMID 30274197, 2018). "According to WHO, type 2 diabetes occurs because either body does not produce enough insulin or body resists the effects of insulin." (PMID 30108647, 2018). "In our study, the severely obese women with cervical cancer, outcomes were not affected by metformin use, type II diabetes, or insulin use." (PMID 29423104, 2018). "Of these intensive regimens, insulin-based protocols, such as continuous subcutaneous insulin infusion (CSII) or multiple daily injections (MDI), are highly effective at reducing hyperglycemia in patients with poorly controlled type 2 diabetes." (PMID 30420969, 2018). "Given that GLP-1 is best known for its ability to facilitate insulin signaling, we next investigated whether liraglutide, a GLP-1 analogue approved and widely used in the treatment of type-2 diabetes, protects against mHTT-induced neurotoxicity." (PMID 30149534, 2018). "TGR5 activity appears to not have been lost in type 2 diabetic humans whereby the infusion of CCK, or rectal taurocholate, causes GLP-1 and insulin release via the TGR5 axis in colonic L-cells and pancreatic β-cells respectively." (PMID 30364192, 2018). "Despite their widespread use in this population, data on the pharmacodynamic (PD) properties of the insulin analogs detemir and glargine in severely obese patients with type 2 diabetes are lacking." (PMID 30114246, 2018). "The shapes of the associations of 2hPG, fasting insulin and HOMA-IR, a measure of insulin resistance, with incident type 2 diabetes have not been extensively studied." (PMID 29018885, 2018). "The Mobile Insulin Titration Intervention (MITI) program helps patients with type 2 diabetes find their correct basal insulin dose without in-person care." (PMID 29555621, 2018). "In the study of middle-aged overweight and obese individuals, including subjects with an impaired glucose tolerance and type 2 diabetes, serum MCP-1 was positively related to fasting and postload glucose and TG and inversely to HDL cholesterol and QUICKI, an index of insulin sensitivity." (PMID 30302090, 2018). "GK rats are a commonly used model of spontaneous nonobese type 2 diabetes with mildly elevated fasting blood glucose, elevated blood glucose after eating, and stable glucose-stimulated insulin secretion disorders and glucose intolerance." (PMID 30687277, 2018). "Carter reported equivalent reductions in HbA1c in individuals with Type 2 diabetes with 12 weeks of IER or CER which had been achieved with greater (albeit non-significant) reductions in insulin medications within the IER group." (PMID 28106818, 2017). "Moreover, the APOA1/HDL cholesterol ratio was the strongest predictor of incident type 2 diabetes, and APOB level is significantly correlated with plasma insulin level in women." (PMID 28549478, 2017).
type 2 diabetes (continued). "Protein tyrosine phosphatase (PTP-1B), is a negative regulator of insulin signaling; it inhibits insulin-stimulated tyrosine phosphorylation of insulin receptor (IR), insulin receptor substrate-1 (IRS-1) and is a therapeutic target for type 2 diabetes." (PMID 28608836, 2017). "Each blood donor with type 2 diabetes reported having a good glycemic control and was not on insulin treatment in accordance with the directive for donating blood in the Netherlands." (PMID 28118412, 2017). "This unique mechanism, independent of insulin secretion and beta cell function, has made this class of medication desirable in patients with type 2 diabetes." (PMID 28634592, 2017). "The debate still continues regarding the effectiveness and value for money of SMBG in people with type 2 diabetes who are not receiving treatment with insulin." (PMID 28143495, 2017). "It is well established that young, lean offspring of parents with type 2 diabetes have greater intramuscular fat and lower whole body insulin sensitivity compared to their counterparts without such family history." (PMID 29280741, 2017). "In contrast, pharmacological augmentation of circulating GIP levels fails to evoke an effective increase in insulin secretion in patients with type 2 diabetes." (PMID 28004148, 2017). "This was highest in people with type 1 diabetes (0.082 events per person per year, 95% CI: 0.073–0.092) and lowest in those with type 2 diabetes who were taking oral glucose-lowering medications that were not insulin secretagogues (group a)." (PMID 28824815, 2017). "Of 117 subjects with type 2 diabetes, at baseline (2007) 22 (18.8%) were prescribed insulin (with or without oral hypoglycaemics), 88 (75.2%) were managed with oral hypoglycaemics and 7 (6.0%) were managed with diet alone." (PMID 28767669, 2017). "Initially, the pancreas responds by secreting more insulin, but when this can no longer compensate for the impaired insulin response of the liver and other organs, type 2 diabetes develops." (PMID 29239299, 2017). "Type 2 diabetes (T2D) arises after insulin secretory function fails to maintain normoglycemia in the face of insulin resistance, often secondary to obesity." (PMID 28592605, 2017). "On other hand, in studies where individuals had yet to be classified with type 2 diabetes, consumption of increased dietary protein was not sufficient to improve insulin sensitivity even when measured with methods that provided enhanced specificity." (PMID 28713581, 2017). "After 20 years of disease, almost all patients with type 1 diabetes, 80% of patients with insulin treated type 2 diabetes and 50% of patients with type 2 diabetes who do not require insulin treatment will have some degree of DR." (PMID 28452939, 2017). "As a consequence the debate continues regarding the value of SMBG in people with type 2 diabetes who are not on insulin therapy." (PMID 28143495, 2017). "An estimated 21–29% of type II diabetics on insulin have never checked their glucose, and only 17–39% check their glucoses on a daily basis." (PMID 28245810, 2017). "Our results indicate that the frequency of preclinical carotid atherosclerosis in patients with adult-onset initially non-insulin requiring autoimmune diabetes, also called LADA, is comparable, even greater, than in adults of similar age with classic type 1 diabetes and type 2 diabetes." (PMID 28750634, 2017). "Vanadium effects glycogen metabolism and gluconeogenesis, lipogenesis, insulin sensitization in Type 2 diabetes etc. and some of these activities do not involve PTPase." (PMID 28072841, 2017). "Obese persons have high blood leptin levels, but they also show leptin resistance and hence, because insulin secretion is not well regulated either, with time can develop type II diabetes." (PMID 28651594, 2017). "The introduction of insulin therapy may improve lipid metabolism and circulating lipids, raising HDL-cholesterol and lowering triglycerides (TGs) in patients with type 2 diabetes." (PMID 28587667, 2017).
type 2 diabetes (continued). "In type 2 diabetes without hemochromatosis, participants randomized to phlebotomy therapy achieved decreased hemoglobin A1c levels and favorable changes in insulin secretion and IR." (PMID 28331855, 2017). "Prevalent cases of type 2 diabetes were individuals using an oral hypoglycemic agent, irrespective of insulin use, in 2012." (PMID 28123753, 2017). "This is the first study to show that CLW improves hepatic insulin sensitivity in non-obese type 2 diabetic rats and suggests that it can be used as an intervention for Asian type 2 diabetes." (PMID 29104217, 2017). "In type 2 diabetes mellitus (T2DM), both glucagon and insulin secretion are impaired." (PMID 28275121, 2017). "Insulin was used to treat 28.1% of women with GDM and 77% of women with type 2 diabetes." (PMID 28197657, 2017). "The aim of this study was to explore the relationship between insulin sensitivity assessed by the Matsuda index and the QTc interval from a standard baseline 12-lead electrocardiogram (ECG) in a large Chinese population with type 2 diabetes." (PMID 28912840, 2017). "Twenty-two subjects were 14–21 years of age and 66 were 22–75 years of age, 62 had type 1 diabetes, 10 had insulin-requiring type 2 diabetes, and 16 had noninsulin-requiring type 2 diabetes." (PMID 28700272, 2017). "Most participants had type 2 diabetes (85.6%), and were taking oral hypoglycaemic drugs (84.7%) rather than insulin or insulin plus oral hypoglycaemic drugs (14.4%), reflecting the distribution of type 1 and type 2 diabetes patients in the trial population." (PMID 28045979, 2017). "Eventually, due to a decline in the secretory rate and a decrease in beta cell mass, impaired insulin secretion fails to compensate, resulting in hyperglycaemia, beta cell destruction and type 2 diabetes." (PMID 28770320, 2017). "The aim of our 6.8-year follow-up study was to investigate the associations of three acute-phase proteins, GlycA, hs-CRP, and IL-1RA, with the changes in insulin sensitivity and insulin secretion in a large cohort of men without known type 2 diabetes." (PMID 28911155, 2017). "Now that GV could affect insulin resistant, so the improvement of GV might have beneficial effects not only on glucose control but also on CVD in type 2 diabetes." (PMID 29164077, 2017). "We here examined cephalic and post-absorptive insulin secretion in 31 non-obese individuals, including matched individuals with and without a known family history of type 2 diabetes (first-degree family history; FDR)." (PMID 28288176, 2017). "Given the functional attributes of AMPK in glucose/lipid homeostasis, body weight, food intake, insulin signaling and mitochondrial biogenesis, AMPK is considered to be a major therapeutic target for the treatment of metabolic diseases including type 2 diabetes and obesity, hence atherosclerosis." (PMID 28178661, 2017). "The SMBG Study is a 12 month, multi-centre, randomised controlled trial in people with type 2 diabetes not on insulin therapy who have poor glycaemic control (HbA1c ≥58 mmol/mol / 7.5%)." (PMID 28143495, 2017). "IR is defined by normal fasting serum glucose associated with high serum insulin levels, a state that results in type 2 diabetes when the increased insulin secretion is no longer able to compensate for impaired peripheral insulin responsiveness." (PMID 29333450, 2017). "INSR gene is involved in 12 pathways of which, Type II diabetes mellitus, PI3K-Akt signaling pathway, Insulin signaling pathway (FDR < 0.05) are prominent related to Type 2 Diabetes whereas CCND1 is involved in Jak-STAT signalling pathway apart from PI3K-Akt signaling pathway." (PMID 28761062, 2017). "However, the effects of insulin therapies on NMR-determined lipoprotein subclasses is limited to selected cohorts of patients with type 1 diabetes and very small studies in type 2 diabetes." (PMID 28587667, 2017).
type 2 diabetes (continued). "In a crossover, randomized study comparing insulin detemir and insulin glargine administered once a day in hospitalized patients who had type 2 diabetes, there was not a significant difference in the glucose control for 55 patients." (PMID 28970434, 2017). "We examined the efficacy of CLW in treating type 2 diabetic symptoms, and the mechanism by which it improves insulin sensitivity and secretory capacity were explored in male Px rats, a non-obese model of type 2 diabetes." (PMID 29104217, 2017). "We here examined the presence of an early cephalic phase of insulin release in 31 well matched individuals without (n = 15) or with (n = 16) a known family history of type 2 diabetes (first-degree relatives; FDR)." (PMID 28288176, 2017). "From 1 January 2011 to 31 December 2012, a significantly higher proportion of people with type 2 diabetes were receiving treatment with non-secretagogues (58.9%) or insulin (18.7%), but fewer were being treated with secretagogues (22.4%)." (PMID 28824815, 2017). "In type 2 diabetes human pancreatic islets, as compared with non-diabetic controls, up - regulation of insulin and expression of miRNA-463-3p and down-regulation of ABCG4 were observed and their expression levels were closely related." (PMID 28761062, 2017). "Type 2 diabetes mellitus (T2DM) is a metabolic disease in which the body does not properly use insulin." (PMID 29209613, 2017). "Type 2 diabetes (T2D) is a disease in which insulin fails to provide the normal tight control of blood glucose concentration." (PMID 29031711, 2017). "The results from these mice and human experiments heavily suggest that RSV is not able to modulate the response to insulin in healthy patients; hence, its role as a prophylactic agent against type 2 diabetes cannot be assured." (PMID 28272357, 2017). "Latent autoimmune diabetes of the adults (LADA), that is patients with adult-onset autoimmune diabetes who do not initially require insulin, represent 4–14% of subjects previously diagnosed with type 2 diabetes." (PMID 28750634, 2017). "Type 2 diabetes never develops without substantial impairment of intrapancreatic insulin secretory capacity." (PMID 28369092, 2017). "Type 2 diabetes arises when the endocrine pancreas fails to secrete sufficient insulin to cope with the metabolic demand because of acquired insulin resistance and β-cell dysfunction." (PMID 28179377, 2017). "Despite a significant reduction of ≈37% in insulin-dependent glucose uptake in the muscles of chronic kidney disease rats (p<0.0001), the development of type 2 diabetes was never observed." (PMID 28459862, 2017). "Animal models for Asian type 2 diabetes should be non-obese and have an insulin secretion capacity that is incapable of maintaining normoglycemia concurrent with insulin resistance." (PMID 29104217, 2017). "It is known that GIP does not modulate glucose-dependent insulin secretion in type 2 diabetes, even at supraphysiological (pharmacological) plasma levels." (PMID 29041949, 2017). "In contrast, patients with type 2 diabetes previously on insulin that were randomized to glargine (basal switch cohort) did not have these changes, suggesting effects of prior insulin treatment." (PMID 28587667, 2017). "This evidence also supports the idea that insulin resistance in skeletal muscle rather than liver is the preliminary defect in the development of metabolism syndrome and type 2 diabetes." (PMID 29046729, 2017). "The SDT rat is a newly developed non-obese type 2 diabetes animal model that spontaneously develops hyperglycemia resulting from reduced insulin secretion." (PMID 29169356, 2017). "Interactions between leptin and insulin signaling, and potential therapeutic uses for leptin in normalizing type 2 diabetes have been described recently." (PMID 28533765, 2017).
type 2 diabetes (continued). "Glucose levels showed a peak at 0.5 h in controls and at 1 h in type 2 diabetic patients without abdominal obesity, insulin and HOMA-IR levels rose significantly in both groups with peak at 1 h." (PMID 28814963, 2017). "Type 2 diabetes was previously known as non-insulin-dependent or adult-onset diabetes, and it results from the ineffective use of insulin by the body." (PMID 28729836, 2017). "Further work is required to establish whether the insulin secretory abnormality in GDM, being of short duration, is more readily reversed than that of type 2 diabetes." (PMID 27817155, 2017). "For the nearly 75% of patients living with type 2 diabetes (T2DM) that do not use insulin, decisions regarding self-monitoring of blood glucose (SMBG) can be especially problematic." (PMID 28545493, 2017). "In this regard, we have previously reported that early-onset very obese type 2 diabetic patients failed to improve VO2max and had no improvement in whole-body insulin sensitivity in response to an exercise intervention." (PMID 29062026, 2017). "In increased insulin resistant states, such as when fed a high fat diet, they develop the symptoms of type 2 diabetes without showing obesity." (PMID 29104217, 2017). "A defect in the postprandial insulin-secretory incretin response, mediated by the gut hormones glucagon-like peptide-1 (GLP-1) and glucose-dependent insulinotropic peptide (GIP), is a specific pathophysiological characteristic of type 2 diabetes." (PMID 28004148, 2017). "Both insulin and amylin responses to food intake are altered in patients with type 2 diabetes and absent in patients with type 1 diabetes, because of autoimmune β-cell destruction." (PMID 28702246, 2016). "Indeed, impaired insulin secretory effectiveness of GIP is now recognised as a specific and important pathophysiological characteristic of type 2 diabetes." (PMID 27032106, 2016). "The beneficial effects of regular aerobic exercise for type 2 diabetics have been well established, which include restoration of glycemic control and reduced insulin resistance without muscle hypertrophy." (PMID 27832095, 2016). "Plasma insulin levels of diabetic mice were more than 2-fold higher than non-diabetic mice indicating insulin resistance in type 2 diabetes." (PMID 27941667, 2016). "Unlike insulin-dependent therapies for type-1 diabetes, the treatment of type-2 diabetes is focused on IR interference to correct hyperglycemia and hyperinsulinemia." (PMID 27164093, 2016). "As for the physical activity of patients with type 2 diabetes, the results of our study support recently released data; however, our study was limited to insulin-treated patients only, which was not the case in other papers." (PMID 27703476, 2016). "Type 2 diabetes (T2D) is a chronic and noncommunicable metabolic disorder characterised by hyperglycaemia resulting from defective secretion and/or action of insulin." (PMID 27894336, 2016). "In type-2 diabetes, the body does not produce enough insulin for proper functioning or the cells do not react to insulin (insulin resistance)." (PMID 27916864, 2016). "Given their central role in the insulin signalling pathway, it is not surprising that male mice lacking Irs1 or Irs2 present with elevated blood glucose or type 2 diabetes, respectively." (PMID 27514532, 2016). "In type 1 and type 2 diabetes, fat and protein can significantly impact postprandial glucose excursions in the absence of sufficient insulin." (PMID 27070641, 2016). "We recently have reported the 24-hour glucose, insulin and glucagon responses to a 72-hour fast compared to a 72-hour macronutrient-sufficient, no-carbohydrate diet in men with type 2 diabetes." (PMID 27453716, 2016). "It is to be discussed whether decreased insulin secretory capacity and/or decreased insulin sensitivity play critical roles in the dominant elevation of 2 h PG and FPG levels in the early stage development of type 2 diabetes." (PMID 26788515, 2016).